RN7SL316P (RNA, 7SL, cytoplasmic 316, pseudogene)
Gene: Miscellaneous RNA gene on chromosome 17 (30,702,504 to 30,702,775, reverse strand). Ensembl gene ENSG00000241631.
Homologues: Orthologues: chimpanzee Metazoa_SRP (99% identical), macaque Metazoa_SRP (80% identical). Paralogues in human: RN7SL231P (97% identical), RN7SL1 (75% identical), RN7SL2 (75% identical), RN7SL3 (75% identical), RN7SL220P (74% identical), RN7SL586P (73% identical), RN7SL709P (73% identical), RN7SL122P (72% identical), RN7SL126P (72% identical), RN7SL213P (72% identical), RN7SL416P (72% identical), RN7SL45P (72% identical), and 704 more.